CYP46A1 (cytochrome P450 family 46 subfamily A member 1)
Description:
P450 monooxygenase that plays a major role in cholesterol homeostasis in the brain. Primarily catalyzes the hydroxylation (with S stereochemistry) at C-24 of cholesterol side chain, triggering cholesterol diffusion out of neurons and its further degradation. By promoting constant cholesterol elimination in neurons, may activate the mevalonate pathway and coordinate the synthesis of new cholesterol and nonsterol isoprenoids involved in synaptic activity and learning (By similarity). Further hydroxylates cholesterol derivatives and hormone steroids on both the ring and side chain of these molecules, converting them into active oxysterols involved in lipid signaling and biosynthesis. Acts as an epoxidase converting cholesta-5,24-dien-3beta-ol/desmosterol into (24S),25-epoxycholesterol, an abundant lipid ligand of nuclear NR1H2 and NR1H3 receptors shown to promote neurogenesis in developing brain. May also catalyze the oxidative metabolism of xenobiotics, such as clotrimazole.
Synonyms: CYP46; CP46
Tractability: Small molecule: a drug acting on it is in phase 2 or 3 trials; a structure with a bound ligand is known; a high-quality ligand is known; it belongs to a druggable protein family. Antibody: UniProt predicts a signal peptide or a membrane-spanning region. PROTAC: its protein half-life has been measured; a small molecule that binds it is known.
Target class: Enzyme; Oxidoreductase
Gene: Protein-coding gene on chromosome 14 (99,684,250 to 99,727,318, forward strand). Ensembl gene ENSG00000036530.
Subcellular location: Endoplasmic reticulum membrane; Microsome membrane; Postsynapse; Presynapse; Cell projection, dendrite
Pathways (Reactome):
Metabolism: Endogenous sterols; Synthesis of bile acids and bile salts via 24-hydroxycholesterol
Gene Ontology:
Molecular function: cholesterol 24-hydroxylase activity; heme binding; steroid hydroxylase activity; testosterone 16-beta-hydroxylase activity; testosterone 6-beta-hydroxylase activity; iron ion binding; monooxygenase activity; oxidoreductase activity, acting on paired donors, with incorporation or reduction of molecular oxygen; steroid 17-alpha-monooxygenase activity
Biological process: cholesterol catabolic process; progesterone metabolic process; xenobiotic metabolic process; bile acid biosynthetic process; nervous system development; protein localization to membrane raft; regulation of long-term synaptic potentiation; sterol metabolic process; C21-steroid hormone metabolic process
Cellular component: dendrite; endoplasmic reticulum; endoplasmic reticulum membrane; postsynapse; presynapse
Genetic constraint (gnomAD): Loss-of-function variants: 19 observed, 55.6 expected, observed/expected ratio (o/e) 0.34, 90% interval 0.24 to 0.5. The upper end of that interval is the gene's LOEUF score, 0.5, which puts it in group 2 of 6, group 1 being the genes least tolerant of losing a copy. Missense variants: 441 observed, 639.69 expected, observed/expected ratio (o/e) 0.69, 90% interval 0.64 to 0.75. Synonymous variants: 264 observed, 254.91 expected, observed/expected ratio (o/e) 1.04, 90% interval 0.94 to 1.15.
Homologues: Orthologues: chimpanzee CYP46A1 (100% identical), macaque CYP46A1 (99% identical), mouse Cyp46a1 (95% identical), pig CYP46A1 (92% identical), dog CYP46A1 (89% identical), rat Cyp46a1 (85% identical), guinea pig CYP46A1 (80% identical), rabbit CYP46A1 (76% identical), tropical clawed frog cyp46a1.3 (52% identical), zebrafish cyp46a1.5 (47% identical), zebrafish cyp46a1.1 (47% identical), zebrafish cyp46a1.3 (43% identical), and 2 more.
Diseases named in the same sentence as CYP46A1 in open-access papers:
CYP46A1 is named in the same sentence as 65 diseases in open-access papers, as found by Europe PMC text mining. Sharing a sentence is not in itself a finding about the gene and the disease. The quoted sentences say what the papers report.
Alzheimer disease (37 papers, 2007 to 2026). A progressive, neurodegenerative disease characterized by loss of function and death of nerve cells in several areas of the brain leading to loss of cognitive function such as memory and language. "Dysregulation of CYP46A1 has been implicated in Alzheimer's disease (AD) and Huntington's disease (HD)." (PMID 41704371, 2026). "Studies indicate that a few gene variations in CYP46A1, including the CYP46A1 T allele, are possible genetic risk factors of Alzheimer’s disease." (PMID 37444065, 2023). "Due to its role in amyloid-beta and 24S-OHC production, as well as its possible involvement as a genetic risk factor, the activation of CYP46A1 has the potential to treat Alzheimer’s disease." (PMID 37444065, 2023). "Reduced levels of CYP46A1 have been associated with other protein misfolding diseases such as Alzheimer’s disease (AD), Parkinson’s disease (PD) and Huntington’s disease (HD) as well as other neurodegenerative diseases e.g. Niemann-Pick disease type C (NPC)." (PMID 33795005, 2021). "Polymorphism of the cholesterol-24S-hydroxylase (CYP46A1) gene is thought to be a risk factor for Alzheimer’s disease (AD)." (PMID 32038226, 2019). "The data of the present work along with the results on CYP46A1 inhibition in a mouse model of Alzheimer's disease highlight a new link between the CYP46A1 deficiency and Alzheimer’s disease, namely abnormal phosphorylation of neuronal cytoskeletal proteins." (PMID 29073233, 2017). "Interestingly, CYP46A1 has been associated with other neurodegenerative diseases, such as Alzheimer’s disease (AD) and Huntington’s disease (HD)." (PMID 39964974, 2025). "For instance, Cyp46a1 overexpression has been associated with benefits in models of Huntington’s disease, spinal cerebellar ataxia, and Alzheimer’s disease but may be detrimental in excitotoxicity models." (PMID 38540675, 2024). "The genes represented by the age‐DMRs included a few notable members such as Cyp46a1 and Abca7, which are involved in cholesterol metabolism and implicated in Alzheimer's disease, and few members of the WNT signaling and mesenchyme developmental pathways (e.g., Fzd1, Fzd8, Wnt5a, Jak3, Ptk7, Nrp2)." (PMID 32790008, 2020). "In addition, reduced Cyp46a1 levels result in cognitive deficits, elevated production of β-amyloid peptides, and abnormal phosphorylation of tau as well as in progressive loss of hippocampal neurons and an Alzheimer's disease–like phenotype." (PMID 30655290, 2019). "Mutations of CYP46A1 may be associated with Alzheimer’s disease." (PMID 27367670, 2016). "The aerobic exercise increased levels of CYP46A1 as well as its metabolite 24-hydroxycholesterol in an APP/PS1 mouse model of Alzheimer’s disease." (PMID 41462691, 2025). "CYP46A1 catalyzes the conversion of brain cholesterol to 24S-hydroxycholesterol, and most studies have focused on Alzheimer’s disease." (PMID 40430847, 2025). "Low-dose EFV allosterically activates CYP46A1, the key enzyme for cholesterol elimination from the brain, and is investigated as a potential treatment for Alzheimer’s disease." (PMID 38396919, 2024). "Dysregulation of brain cholesterol turnover and reduced CYP46A1 levels are observed in Alzheimer’s disease (AD)." (PMID 38266095, 2024). "EFV is known to be a CYP46A1 activator at low doses and has been explored for the treatment of Alzheimer’s disease." (PMID 36623884, 2023). "A small dose of the anti-HIV drug efavirenz (EFV) was previously discovered to activate CYP46A1, a cholesterol-eliminating enzyme in the brain, and mitigate some of the manifestation of Alzheimer’s disease in 5XFAD mice." (PMID 35721135, 2022). "In summary, the ACAT and CYP46A1 manipulations suggest that biosynthesis of the CE cargo of LDs can be harmful, contributing to the pathogenesis of Alzheimer’s disease." (PMID 35493070, 2022). "At small doses, EFV allosterically activates CYP46A1 in mice and humans and mitigates some of the Alzheimer’s disease manifestations in 5XFAD mice, an animal model." (PMID 35887013, 2022).
Alzheimer disease (continued). "We have previously shown that allosteric CYP46A1 activation by low-dose efavirenz in a transgenic mouse model of Alzheimer’s disease (AD) enhanced both cholesterol elimination and turnover in the brain and improved animal performance in memory tests." (PMID 36581878, 2022). "A clinical trial is in progress to evaluate the effects of efavirenz (EFV), a CYP46A1 activator, on people with mild cognitive impairment due to Alzheimer’s disease (ClinicalTrials.gov: NCT03706885)." (PMID 34235635, 2021). "Brain sterol flux is decreased in Cyp46a1−/− mice compared to wild-type mice and increased in 5XFAD mice (a model of Alzheimer’s disease) when they are treated with a small dose of efavirenz, a CYP46A1 activator." (PMID 34235635, 2021). "Conversely, increased expression of CYP46A1 improves spatial memory retention in aged female mice and reduces cognitive decline and amyloid burden in several mouse models of Alzheimer's disease (29, –, 31)." (PMID 30655290, 2019). "Up to now, positive CYP46A1 immunostaining of axons in the white matter was only seen in the normal human brain and in the brains of Alzheimer’s disease patients." (PMID 28578430, 2017). "The most successful and advanced drug for Alzheimer’s disease that activates CYP46A1 is Efavirenz." (PMID 37444065, 2023). "Importantly, low dose EFV was already confirmed to be safe and activate CYP46A1 in the brain of human subjects with early Alzheimer’s disease." (PMID 37392222, 2023). "In addition to these two genes, the proteins SREBP2, TREM2, LRP1, and the CYP46A1 gene are all additional candidates as targets to combat Alzheimer’s disease due to their involvement in the metabolic pathway of cholesterol in the brain." (PMID 37444065, 2023). "Cholesterol and 24S-hydroxycholesterol, which is formed from cholesterol via the Cytochrome P450 46A1(CYP46-A1) enzyme, are involved in the neuropathology of Alzheimer’s disease, and the primary genetic risk factor for Alzheimer’s disease is apolipoprotein E-ε4." (PMID 29065513, 2017). "Consistent with this, a chemical activator of cholesterol 24-hydroxylase (CYP46A1) increased 24-hydroxycholesterol secretion from APP mutant iPSC-derived neurons (but not astrocytes) lowering CEs and increasing proteosomal degradation of phosphorylated Tau, a hallmark of Alzheimer’s Disease." (PMID 35493070, 2022). "By utilizing existing clinical date from DisGeNET and undergoing protein-protein network analysis on cholesterol metabolism and Alzheimer’s disease, the top target genes selected were GSK3B, BACE1, SREBP2, CYP46A1, ABCA1, and TREM2." (PMID 37444065, 2023). "This laboratory discovered CYP46A1 activation by pharmacologic means, namely, by EFV, and tested two paradigms of EFV treatment in 5XFAD mice, a model of Alzheimer’s disease." (PMID 34235635, 2021). "In this work, protein-protein interaction analysis was conducted based upon the genes from a clinical database to identify the top protein targets with most data-indicated involvement in Alzheimer’s disease, which include ABCA1, CYP46A1, BACE1, TREM2, GSK3B, and SREBP2." (PMID 37444065, 2023). "In addition, 24S-OHC accumulation due to abnormal expression of CYP46A1 and CYP39A1 results in neuronal death, contributing to Alzheimer’s disease (AD)-related neurodegeneration." (PMID 32392803, 2020). "The selective expression of CYP46A1 around neuritic plaques and the potent inhibition of APP processing in neurons by 24(S)-hydroxycholesterol suggest that CYP46A1 affects the pathophysiology of Alzheimer's disease." (PMID 23119149, 2012). "CYP46A1 activation by EFV was found to increase tissue levels of the biologically active sterol 24HC, the rate of tissue cholesterol turnover, and mitigate the disease manifestations in mouse models of Alzheimer’s disease, depression, Niemann-Pick disease type C, glioblastoma, and prion disease." (PMID 37392222, 2023).
Huntington disease (17 papers, 2018 to 2026). Huntington disease (HD) is a rare neurodegenerative disorder of the central nervous system characterized by unwanted choreatic movements, behavioral and psychiatric disturbances and dementia. "Although mutations in CYP46A1 have been associated with neurodegenerative diseases such as Alzheimer’s and Huntington’s disease in humans, the function of CYP46A1 in teleosts has not been studied." (PMID 29295707, 2018). "Restoring CYP46A1 activity and cholesterol homeostasis through allosteric modulation or viral vector delivery is a therapeutic goal in Huntington's disease (ClinicalTrials.gov: NCT05541627)." (PMID 40045480, 2025). "As was reported, CYP46A1 expression is decreased in the putamen of HD patients, in the striatum of R6/2 mice (a HD mouse model), and in striatal Huntington’s disease cell lines (by transfection of mutant huntingtin gene)." (PMID 37308953, 2023). "In Huntington’s disease (HD), several enzymes involved in cholesterol metabolism are downregulated, among which the neuronal cholesterol 24-hydroxylase, CYP46A1, is of particular interest." (PMID 37446179, 2023). "In humans and mouse models, CYP46A1 activity is altered in Alzheimer’s and Huntington’s diseases, spinocerebellar ataxias, glioblastoma, and autism spectrum disorders." (PMID 34305573, 2021). "Dysregulation of CYP46A1 expression has been shown to occur in several neurodegenerative diseases, including Parkinson's, Alzheimer's and Huntington diseases." (PMID 31777202, 2020). "As a case in point, a recent study shows that the expression of Cyp46a1 is decreased in the striatum of a mouse model of Huntington’s disease (HD) and a gene therapy aproach to induce the expression of CYP46A1 is suggested as a potential treatment for HD." (PMID 32132201, 2020). "Conversely, increased levels of CYP46A1 in the R6/2 Huntington's disease mouse model decreased striatal neuron atrophy, protein aggregates, and motor deficits." (PMID 30655290, 2019). "With regard to neurodegeneration in the basal ganglia, it has been reported that the level of CYP46A1 is decreased in the putamen of patients with Huntington's disease." (PMID 30655290, 2019). "The study provides the evidence that the neuroprotective role of CYP46A1 in Huntington’s disease." (PMID 37308953, 2023). "Literature data tend to indicate that cholesterol overload might be neurotoxic and that the recovery of cholesterol status displays a neuroprotective effect, as has been shown by CYP46A1 overexpression in a Huntington’s disease mouse model." (PMID 35275950, 2022). "Animal studies have demonstrated that increases in CYP46A1 activity by genetic or pharmacologic means can be beneficial in models of Alzheimer’s and Huntington’s diseases, Niemann-Pick disease type C, spinocerebellar ataxia, depression, glioblastoma and prion disease." (PMID 34235635, 2021).
cognitive deficits (15 papers, 2016 to 2025). "Fourth, the APOE ε4 allele is a key factor in the onset of AD and MCI; it exerts a remarkable influence on the relationship between the polymorphism of CYP46A1 and the onset of cognitive impairment." (PMID 34054500, 2021). "It has been shown that CYP46A1 deficiency leads to neuronal dysfunction, neuronal death, motor and cognitive impairments and that CYP46A1 overexpression improved neurodegenerative HD-related traits." (PMID 32276655, 2020). "We hypothesize that ATAD3A oligomerization might cause AD-associated neuropathology and cognitive deficits by suppressing CYP46A1-mediated brain cholesterol metabolism." (PMID 35236834, 2022). "In patients with T2DM, high plasma level of 24-OHC and the CC genotype carrier of CYP46A1 rs754203 may portend a high risk of developing early cognitive impairment, including attention and executive deficits." (PMID 34054500, 2021). "This may explain some of the possible mechanisms between the CYP46A1 gene polymorphism and the occurrence of cognitive impairment." (PMID 34054500, 2021). "Our research have found that, in patients with T2DM, high plasma level of 24-OHC and the CC genotype carrier of CYP46A1 rs754203 may portend a high risk of developing early cognitive impairment, including attention and executive deficits." (PMID 34054500, 2021). "In conclusion, the evaluations of the Cyp46a1-/- brain brought attention to the previously unconsidered compensatory responses, pathways, and proteins that may underlie cognitive deficits in Cyp46a1-/- mice." (PMID 29073233, 2017). "Decreased expression of CYP46A1 in mice was found to increase the amount of cholesterol in neurons, which led to apoptotic death and cognitive deficits." (PMID 37444065, 2023). "Of note, the injection of an adeno-associated virus-CYP46A1 vector brought CYP46A1 and 24-OHC content back to control levels and the cognitive deficits were remedied, whereas tau hyperphosphorylation and gliosis were unaffected." (PMID 36978879, 2023). "For example, CYP46A1 overexpression to accelerate brain cholesterol clearance reduces amyloid pathology and improves cognitive deficits in murine models for AD." (PMID 36076005, 2022). "This study aimed to investigate the roles of 24-OHC and the CYP46A1 (rs754203) polymorphism in patients with T2DM and mild cognitive impairment (MCI)." (PMID 34054500, 2021). "In a model of the AD-like tau pathology (THY-Tau22 mice), the CYP46A1 gene therapy completely restored impaired cholesterol metabolism, rescued cognitive deficits, and mitigated impairments in long-term depression (LTD) as well as spine defects that characterize this model." (PMID 34305573, 2021). "In CYP46A1-deficient mice, despite unchanged brain cholesterol levels, cholesterol synthesis decreases by 40%, possibly compensating for the lack of degradation, resulting in severe cognitive deficits and impaired synaptic plasticity." (PMID 40126262, 2025). "In our study, ovariectomy led to cognitive deficits in female Wt mice, especially in the MWM test, that were significantly mitigated by CYP46A1 overexpression." (PMID 38266095, 2024). "Reproducible demonstrations in mouse models of AD of beneficial effects of the CYP46A1 expression increase or CYP46A1 pharmacologic activation justified the safety and tolerability phase 1 study of EFV (Sustiva) in patients with mild cognitive impairment due to AD (NCT03706885 trial called EPAD)." (PMID 34305573, 2021). "Activation of CYP46A1 by low-dose Efavirenz, a non-nucleoside reverse transcriptase inhibitor is a therapeutic target that is currently under evaluation in a randomized clinical trial in patients with mild cognitive impairment due to AD43,45." (PMID 34075056, 2021).
cognitive decline (7 papers, 2012 to 2025). "For instance, reduced CYP46A1 activity has been linked to amyloid-beta accumulation and cognitive decline in AD, while altered CYP2D6 expression in the basal ganglia correlates with increased susceptibility to PD." (PMID 40126262, 2025). "Clinically, CYP46A1 is particularly significant since early menopause—a female-specific risk factor—is associated with cognitive decline and exacerbated AD pathology." (PMID 40126262, 2025). "Previous work in this strain has shown that aging increases CYP46A1 levels in the hippocampus of 24-month-old mice, leading to cholesterol loss and cognitive decline." (PMID 37619212, 2023). "Regulation of pTau by CYP46A1 is also conserved in adult (mice) brains where genetic inhibition of CYP46A1 enhances abnormal phosphorylation of Tau, and overexpression of CYP46A1 in transgenic Tau mice rescues cognitive decline." (PMID 30686764, 2019). "Indeed, cognitive decline in Cyp46a1−/− mice has been related to reduced amounts of a freshly synthesized nonsterol isoprenoid geranylgeraniol, which is produced in the mevalonate pathway and is required for long-term potentiation." (PMID 34235635, 2021). "This study describes the molecular mechanisms by which CYP46A1 modulates neuronal outgrowth and function, highlighting the cholesterol 24-hydroxylase as an attractive drug target in the physiological and pathological context of cognitive decline and brain disorders." (PMID 27491694, 2016).